SAE1 (SUMO1 activating enzyme subunit 1)
Diseases named in the same sentence as SAE1 in open-access papers (continued):
Sharing a sentence is not in itself a finding about the gene and the disease.
macrophage activation syndrome (1 paper, 2022). A complication of rheumatic disease that is caused by excessive activation and uncontrolled proliferation of T lymphocytes and well-differentiated macrophages. "Two patients tested positive for anti-MDA5 antibodies: one of them (also positive for anti-Ro52 antibodies) underwent fatal macrophage activation syndrome, the other (also positive for anti-SAE-1 antibodies) died due to pneumonia." (PMID 35833112, 2022).
non-small cell lung carcinoma (1 paper, 2022). A group of at least three distinct histological types of lung cancer, including non-small cell squamous cell carcinoma, adenocarcinoma, and large cell carcinoma. "Finally, the results of the CCK-8 assay, cell cycle analysis, and transwell assay demonstrated that the two risk genes, SAE1 and UBA2, could promote proliferation and migration in non-small cell lung cancer cells." (PMID 35606717, 2022).
Ogden syndrome (1 paper, 2025). Ogden syndrome is a rare, genetic progeroid syndrome characterized by a variable phenotype including postnatal growth delay, severe global developmental delay, hypotonia, non-specific dysmorphic facies with aged appearance and cryptorchidism, as well as cardiac arrthymias and skeletal anomalies. "Combined analyses of Ogden syndrome cellular models and HeLa cancer models identified a subset of common N-terminally acetylated proteins, including GCN1, ELOA, PPIA, RPL13A, RPP30, and SAE1." (PMID 40558489, 2025).
pancreatic cancer (1 paper, 2023). "Among them, SAE1 is an E1-like protein and is involved in the development and progression of several cancers, such as breast, liver, and pancreatic cancer." (PMID 37705041, 2023).
rectal cancer (1 paper, 2017). A primary or metastatic malignant neoplasm that affects the rectum. "Patients in the group carrying anti-SAE1 antibodies also had cervical, lung, esophageal and rectal cancers." (PMID 29178913, 2017).
renal cell carcinoma (1 paper, 2020). "We can see that SENP5, SENP3, UBE2I, PIAS3, TRIM27, SAE1, and CBX4 are risk factors in the development of renal cell carcinoma." (PMID 33123273, 2020).
systemic lupus erythematosus (1 paper, 2020). An autoimmune multi-organ disease typically associated with vasculopathy and autoantibody production. "Of the strong false positive Abs (n = 7), 5 were MSAs (n = 1 for each of anti-EJ, anti-Mi2A, anti-SAE1, anti-SRP, anti-PL12), and 2 were MAAs (anti-Ku in a patient with resolved undifferentiated connective tissue disease and anti-PM-SCL75 in a patient with systemic lupus erythematosus)." (PMID 32699830, 2020).
cancer (27 papers, 2015 to 2025). A tumor composed of atypical neoplastic, often pleomorphic cells that invade other tissues. "Classically, TIF1γ, NXP2 and SAE1 antibodies delimit a subset of subjects under a high risk of cancer, indicating the need for neoplastic screening and close monitoring, especially in the first 3 years after the onset of symptoms." (PMID 39835155, 2024). "SAE1 is highly expressed in various malignant tumors and is closely associated with the tumorigenesis and tumor development." (PMID 39742381, 2024). "In cancer, SAE1 has been implicated in the regulation of tumor growth and metastasis, as well as the response to chemotherapy and radiation therapy." (PMID 37886949, 2023). "Mutations in the SAE1 gene have been linked to several diseases, including cancer, neurological disorders, and skeletal dysplasia." (PMID 37886949, 2023). "A recent study reported that SAE1 is associated with dysregulated cancer metabolic signaling in HCC and contributed to the migration and invasion of HCC cells." (PMID 35859792, 2022). "The oncogenic effect of upregulated SAE1 is associated with dysregulated cancer metabolic signaling." (PMID 33477333, 2021). "In conclusion, the present study demonstrates that SAE1 is a targetable cancer metabolic biomarker with high potential diagnostic and prognostic implications for patients with HCC." (PMID 33477333, 2021). "In the current study, we found that anti-NXP2 and anti-SAE1 are also associated with an increased risk of cancer, in addition to anti-TIF1-γ." (PMID 29178913, 2017). "In this study, hypothesizing that SAE1 is implicated in HCC metastatic phenotype and poor prognosis, we analyzed the expression of SAE1 in several cancer databases and to unravel the underlying molecular mechanism of SAE1-associated hepatocarcinogenesis." (PMID 33477333, 2021). "Initially we evaluated SAE1 mRNA expression levels in several human cancers by analyzing TCGA RNA-sequencing data in the TIMER database." (PMID 38351014, 2024). "We searched for the SAE1 expression in the cancer database and further verified it with a tissue microarray." (PMID 38351014, 2024). "Knocking down SAE1 in cancer cells has been shown to inhibit cell proliferation, which aligns with our findings that heat stress inhibits SAE1 expression and consequently cell proliferation." (PMID 39594483, 2024). "As the most abundant E1 SUMO–activating enzyme in cancer, SAE1 initiates SUMOylation modification by catalyzing the C-terminal adenylation of SUMOs." (PMID 35579947, 2022). "We divided patients into two groups based on the median expression of SAE1 in these two datasets and conducted GSEA, a widely used method to shed light on the biological function of a specific gene, to understand the role of SAE1 in these two types of cancer." (PMID 35859792, 2022). "Knocking down HNRNPC and IGF2BP3 in cancer cells led to decreased levels of SAE1, probably through the regulation of mRNA stability." (PMID 35859792, 2022). "Accruing evidence from numerous studies have suggested that dysregulated SAE1 expression and/or activity contributes to uncontrolled cell proliferation, development of cancer, angiogenesis, invasion and metastasis." (PMID 33477333, 2021). "Potential relevancy between malignant diseases and SUMOylation pathway has been put forward and analogously the aberrant SAE1 was proved to be a partaker in cancer development." (PMID 34621746, 2021). "Among these proteins, SAE1 was reported to be highly expressed in a variety of cancers and promotes tumor progression as well as poor prognosis." (PMID 32612956, 2020). "Our study demonstrates in what is, to our knowledge, the largest population examined to date, that anti-SAE1, and previously reported anti-TIF1-γ and anti-NXP2 antibodies, are all associated with an increased risk of cancer in patients with IIMs." (PMID 29178913, 2017). "For example, the expression of SAE1/2 is significantly upregulated in cancer tissues of HCC patients." (PMID 29021212, 2017).
cancer (continued). "Intriguingly, the AKT SUMOylation is mediated by SAE1, suggesting that SAE1 methylation may suppress cancer cell proliferation by reducing AKT SUMOylation." (PMID 39127633, 2024). "Overall, SAE1 is an important protein that plays a critical role in the regulation of cellular processes and disease development, and it is an active area of research in various fields, including cancer biology and drug discovery." (PMID 37886949, 2023). "Some studies have suggested that inhibiting SAE1 activity may be a potential strategy for cancer treatment." (PMID 37886949, 2023). "The results showed that genes in the high-SAE1 group were enriched in “cell cycle,” “oocyte meiosis,” and “DNA replication,” suggesting a general role of SAE1 in the cell cycle regulation in the two types of cancer." (PMID 35859792, 2022). "We conducted a pan-cancer analysis of SAE1 by manipulating data from the TCGA database to understand whether the function of SAE1 in cell cycle regulation was confined to HCC or a general phenomenon in solid tumors." (PMID 35859792, 2022). "In addition, pan-cancer analyses also demonstrated that SAE1 was related to the cell cycle in some other types of cancer, implicating that the role of SAE1 was probably not cancer type specific." (PMID 35859792, 2022). "In the present study, hypothesizing that SAE1 is implicated in HCC metastatic phenotype and poor prognosis, we investigated the variability of SAE1 expression in several cancer databases and its probable implication in HCC progression." (PMID 33477333, 2021). "The overexpression of SAE1 is correlated with the poor prognosis of patients, which suggests that SUMOylation may involve in the progression of malignant tumors." (PMID 33273928, 2020). "A dysregulation of SAE1 expression involves in progression of several human cancers." (PMID 31345225, 2019). "In this large longitudinal cohort study, we demonstrated that patients with IIM who carry anti-TIF1-γ, anti-NXP2, or anti-SAE1 antibodies, and those who are MSAs-negative have increased risk of cancer compared to age-matched and sex-matched control subjects." (PMID 29178913, 2017). "Among 72 IIM patients with malignancies in a cohort study from Northern China, 38 tested positive for anti-TIF1-γ, 3 for anti-NXP2, 4 for anti-SAE1, 10 for anti-ARS, 1 each for anti-MDA5, anti-HMGCR, and anti-SRP." (PMID 41280916, 2025). "The expression of SUMOylation cascade proteins, such as SENP, SUMO-activating enzyme subunit 1 (SAE1)/2, UBC9, and E3 ligases, is upregulated in different types of cancer." (PMID 37705041, 2023). "Recent studies found that the dysregulation of SUMOylation contributed to the initiation and development of cancer, and that most SUMO-related genes, including SUMO-2 and SUMO-activating enzyme subunit 1 (SAE1), were overexpressed in many types of tumor." (PMID 35859792, 2022). "SUMO E1 activating enzyme is a heterodimer formed by SAE1 and SAE2, and the expression of SUMO E1 can be detected in many kinds of malignant tumors." (PMID 33273928, 2020). "Recently, there are many studies have shown that expression of the SUMO E1 activating enzyme (a heterodimer of SAE1 and SAE2), the SUMO E2 conjugating enzyme (Ubc9) or the SUMO E3 ligases appears to be enhanced in numerous cancers." (PMID 29021212, 2017). "Notably, SAE1 protein was overexpressed in RMS tissues and cells, positioning it as a potential biomarker for this cancer." (PMID 40549307, 2025). "Strikingly, SS was the most sensitive subtype of cancer to knocking down UBE2I (UBC9), SUMO2 (the most widely expressed SUMO in humans), PIAS1, SAE1 and UBA2 (SAE2), molecules encompassing the entire SUMOylation process and pointing to a selective dependency of SS on this PTM." (PMID 38883782, 2024).
tumor (21 papers, 2012 to 2025). "In particular, in HCC, SAE1 expression is closely correlated with the tumor stage, metastatic phenotype, and survival rate, indicating that SAE1 has excellent diagnostic value in HCC." (PMID 37705041, 2023). "In our study, we first found that high expression of SAE1 was significantly associated with poor prognosis in ICC patients and that SAE1 significantly promoted tumor proliferation and migration." (PMID 37705041, 2023). "The SAE1 overexpression was significantly associated with the tumor size, tumor-node-metastasis stage, estrogen receptor, progesterone receptor, human epidermal growth factor receptor 2, and whether or not it was a triple-negative BC." (PMID 39742381, 2024). "In addition, we demonstrated that underlying the oncogenic and HCC-promoting activity of SAE1 was its ability to upregulate oncogenic effectors of cell cycle progression while downregulating FOXO1-associated tumor suppressing signaling." (PMID 33477333, 2021). "Additionally, SAE1 expression was significantly associated with the tumor size, TNM stage, ER, PR, and HER2 expression, and whether or not it was TNBC." (PMID 39742381, 2024). "This induces acetaldehyde metabolic dysfunction and drives tumor metabolic reprogramming, with SAE1-mediated KLF9 inhibition correlating positively with poor prognosis and metastatic risk in HCC patients." (PMID 40860800, 2025). "Although mechanistic details of KLF9’s role remain unexplored in this context, its inclusion in SAE1-regulated tumor suppression networks suggests potential involvement in SAE1-driven HCC progression and metastasis." (PMID 40860800, 2025). "We further used the TCGA database to confirm the higher SAE1 expression in tumor tissues compared with adjacent tissues, which was in line with IHC analysis from a GC tissue microarray." (PMID 38351014, 2024). "Our results showed that treatment with SAE1 siRNA attenuated tumor growth at 21, 28, 35, and 42 days." (PMID 37886949, 2023). "SAE1 inhibitors have been suggested as a potential therapeutic target because they can interfere with the growth and spread of tumor cells." (PMID 37705041, 2023). "To further investigate the association between SAE1 and Circ-RAPGEF5, we performed the FISH assay in tissue microarrays containing 91 tumor tissues of patients with ICC." (PMID 37705041, 2023). "Circ-RAPGEF5 promotes ICC tumor progression and SUMOylation by acting as a sponge for miR-3185 to stabilize SAE1." (PMID 37705041, 2023). "Considering that DNA methylation is mostly associated with transcriptional repression, we expected that hypomethylation occurred in the SAE1 CpG site in tumor samples because SAE1 was upregulated in HCC." (PMID 35859792, 2022). "In these two independent cohorts, both SUMO2 and SAE1 showed a significantly higher expression in tumor samples than in normal ones." (PMID 35859792, 2022). "The IHC staining on collected tumor samples from our hospital supported that SAE1 was overexpressed in HCC and strongly correlated with the Ki67 index." (PMID 35859792, 2022). "Further, 47 paired HCC samples and corresponding tumor-adjacent normal ones were subjected to the HE or IHC staining of SAE1 and Ki67." (PMID 35859792, 2022). "Consistent with previous studies, SAE1 and Ki67 were predominantly located in the nucleus of cells, and SAE1 had significantly stronger staining in tumor samples than in normal livers." (PMID 35859792, 2022). "SUMO-2 and SAE1 were highly expressed in tumor cells, and their low levels correlated with the longer survival of patients with HCC." (PMID 35859792, 2022). "Using the default cutoff value of the GEPIA2 (|Log2FC| cutoff = 1, and q-value cutoff = 0.01), we found that SUMO2 and SAE1 were significantly upregulated in the tumor samples compared with normal livers." (PMID 35859792, 2022). "The correlation between the expression of SAE1 and the methylation of SAE1 or quantity of tumor-infiltrating immune cells was further invested." (PMID 34621746, 2021).
tumor (continued). "More so, compared with SAE1 expression in non-tumor, the AUCs for SAE1 expression in patients with stages I, II, III, and IV were 0.92 (p < 0.0001), 0.93 (p < 0.0001), 0.94 (p < 0.0001), and 1.00 (p = 0.0003), respectively." (PMID 33477333, 2021). "Simultaneously, correlation analysis between SAE1 and the quantity of tumor-infiltrating immune cells in the TNBC tumor microenvironment displayed a negative outcome." (PMID 34621746, 2021). "Compared with adjacent normal tissues, the mRNA expression of SAE1 was increased in TNBC tissues, and the upregulation of SAE1 in TNBC tumor tissues was revealed with a poor prognosis (DFS) for TNBC patients." (PMID 34621746, 2021). "SAE1 has been found to be a relevant biomarker for progression and prognosis in several tumor types." (PMID 34621746, 2021). "At the 35 days’ cell injection time, the average tumor size of SAE1-overexpressing mice was up to 1170.8 ± 135.2 mm3, which was 1.44-fold large as the control with 814.3 ± 196.7 mm3 (P < 0.01)." (PMID 31345225, 2019). "The mean tumor weight from SAE1-overexpressing mice was 3.54 ± 0.62 g after cell injection for 35 days, which was almost 1.53-fold heavy as the control group with 2.31 ± 0.38 g (P < 0.01)." (PMID 31345225, 2019). "The mean tumor weight from mice with low SAE1 expression was 2.29 ± 2.40 g after cell injection for 29 days, which was almost 1.97-fold heavy as the control group with 1.16 ± 1.10 g (P = 0.19)." (PMID 31345225, 2019). "Protein-protein interaction analysis revealed SAE1 could suppress KLF9 alongside other tumor suppressors while activating oncogenic pathways." (PMID 40860800, 2025). "Therefore, it can be stated that SAE1 plays an important role in the regulation of tumor progression in CRC." (PMID 37886949, 2023). "The regulation of Circ-RAPGEF5 and SAE1 could hold significant therapeutic value in the management, which was confirmed by the slowing of tumor growth due to our injection of Sh-Circ-RAPGEF5 lentiviral solution." (PMID 37705041, 2023). "Besides, a significant positive correlation was observed between the expression of HNRNPC and that of SAE1 in tumor samples of both the TCGA_LIHC and ICGC_LIRI datasets (r = 0.43–0.69)." (PMID 35859792, 2022). "Moreover, the patients with LN metastasis or advanced tumor stage had higher serum EV-packaged hnRNPA1, SAE1, and PROX1 expression levels." (PMID 35579947, 2022). "However, the exact mechanism of SAE1 in regulating the cell cycle and proliferation of tumor cells requires further exploration." (PMID 35859792, 2022). "Expectedly, patients with residual tumor (R1 and R2) has higher expression of SAE1 compared with R0 (p = 0.958), and statistically significant upregulation of SAE1 was observed in the deceased compared to those alive (p = 0.025) and equivocal for radiation therapy." (PMID 33477333, 2021). "Because it has been reported that SUMO-1 promotes glycolysis in tumor cells, we investigated whether SAE1/UBA2-mediated SUMOylation is involved in regulating glycolytic metabolism in RA FLSs." (PMID 32938830, 2020). "Similarly, the SAE1 downregulation-mediated signaling molecules were detected in tumor tissues by Western blot, among which their expressions were contrary to the SAE1 upregulation-induced protein changes." (PMID 31345225, 2019). "In addition, using SAE1 siRNA confirmed the correlation between SAE1 and tumor progression." (PMID 37886949, 2023). "Therefore, we performed a correlation analysis of SAE1 expression with the quantity of 10 tumor-infiltrating immune cells (T cells, CD8 T cells, cytotoxic lymphocytes, B lineage, NK cells, monocytic lineage, myeloid dendritic cells, neutrophils, endothelial cells, and fibroblasts)." (PMID 34621746, 2021). "We further discovered that Circ-RAPGEF5 competitively binds miR-3185 to stabilize SAE1 from degradation, promote overall AKT SUMOylation, and induce tumor proliferation and migration." (PMID 37705041, 2023).